FGFR1 (fibroblast growth factor receptor 1)
Diseases named in the same sentence as FGFR1 in open-access papers (continued):
Sharing a sentence is not in itself a finding about the gene and the disease.
tumor (continued). "FGFR1, in particular, has been extensively studied and recognized as an oncogene that fosters tumor development, underscoring its critical role in cancer progression." (PMID 40934169, 2025). "On the other hand, TST003 significantly decreases tumor cell proliferation and spheroid formation capacity by inhibiting the FGFR1/MAPK signaling axis, demonstrating potential antitumor activity in various refractory solid tumor models." (PMID 40066442, 2025). "In a study screening 33 HGG cases for FGFR1 region duplication in the tyrosine kinase domain, only one tumor was found to be positive for FGFR1-TKDD." (PMID 40628732, 2025). "This tumor, which was diagnosed as an anaplastic oligoastrocytoma (WHO grade III) that had progressed from a grade II tumor, exhibited FGFR1-TKDD positivity." (PMID 40628732, 2025). "Prominently, elevated levels of a variety of transcription factors linked with tumor progression, such as EGFR, FOXM1, STAT3, FGFR1, and GATA6, were identified in the high PANO subtype." (PMID 40918470, 2025). "In order to investigate the effects of the novel variant of FGFR1 found in the patient on gonadal cells, we utilized KGN cells, which are human ovarian granulosa-like tumor cells that are widely used for examining the regulation of gonadal steroidogenesis." (PMID 40141355, 2025). "From a therapeutic perspective, lenvatinib’s inhibition of FGFR1 not only suppresses tumor growth but also improves the immune landscape in HCC." (PMID 41226200, 2025). "In contrast to the migration inhibitory role of E‐cadherin, N‐cadherin promotes tumour‐host cell contact by facilitating collective cell migration, enhancing FGFR‐1 signalling and regulating canonical Wnt signalling, thereby promoting tumour cell migration." (PMID 40665565, 2025). "These cells secrete FGF11 to activate the FGFR1 signalling pathway, thereby promoting the expansion of tumour stem-like cells and showing a strong correlation with T cell exhaustion." (PMID 40630800, 2025). "These inhibitors work by reducing FGFR1 activity, which is often overexpressed in certain cancers, thereby impeding tumor growth." (PMID 40934169, 2025). "The ability of nintedanib to maintain FGFR1 signaling suppression, even in resistant tumor subclones, offers a clinical benefit by delaying progression and overcoming resistance mechanisms, particularly when used in combination therapies." (PMID 41226200, 2025). "For example, in RCC, FGFR1 expression is detected in 98% of primary tumor cells and 82.5% of metastatic cells in lymph nodes." (PMID 40547805, 2025). "We and others have previously shown that the PDGFRA and FGFR1 RTKs are important for the survival of malignant rhabdoid tumour cells and complete suppression of PDGFRA is necessary to achieve cell death." (PMID 40781553, 2025). "They transmit signals through four tyrosine kinase receptors (FGFR1–4) and play critical regulatory roles in embryonic development, tumor progression, tissue repair, and cellular metabolism." (PMID 41551579, 2025). "Our PDX model featured high levels of both FGFR1 and PD-L1, and tumor growth in the control group was aggressive." (PMID 40547805, 2025). "Fibroblast growth factor receptor 1 (FGFR1) is recognized as an oncogene that fosters tumor development, playing a vital role in cancer progression." (PMID 40934169, 2025). "Our genomic analysis showed copy number disruption of FGFR1/2 across the cell lines; a result reflected in our human UPS tumour datasets where FGFR1 was CN altered in 60% of cases and FGFR2 in 50%." (PMID 40415599, 2025). "EGFR, ERBB2, and FGFR1 are known to promote tumor growth and survival independently of AR signaling." (PMID 40429793, 2025).
tumor (continued). "Specifically, IGFBP7 has been shown to augment tumor-associated macrophage (TAM) infiltration, thereby promoting GC advancement, through the activation of the FGF2/FGFR1/PI3K/AKT signaling axis." (PMID 40485724, 2025). "Elevating IGFBP7 level promotes tumor progression by enhancing TAM/M2 macrophage polarization through the FGF2/FGFR1/PI3K/AKT axis in GC59,60." (PMID 40032943, 2025). "Due to its role in tumor angiogenesis, FGFR1 is considered a promising target for therapeutic intervention." (PMID 38792249, 2024). "Sequencing of the tumor showed FGFR1-tyrosine kinase domain internal tandem duplication (FGFR1-KD-ITD)." (PMID 38854731, 2024). "The smooth muscle cells, fibroblasts, and B cells exhibited high expression of FGF1, while tumor cells, smooth muscle cells, T cells, and B cells highly expressed FGFR1." (PMID 38407266, 2024). "We used a series of inhibitors to reverse the FGF2 effect on tumor growth, which elucidated paradoxical growth of cancer cells following FGFR1 inhibition in cells with FGFR1 amplification." (PMID 38553760, 2024). "The efficacy of FGFR1-targeted therapies varies depending on the specific genetic alterations and the type of tumor." (PMID 39590377, 2024). "The upregulation of FGFR1 provides an autocrine growth loop for tumor cells, allowing them to continue growing and proliferating despite EGFR inhibition." (PMID 39590377, 2024). "EMT-mediated activation of FGFR1 and β3 integrin complexes promotes metastatic tumour growth by enhancing local focal adhesion kinase (FAK) activity." (PMID 40135140, 2024). "Using a monoclonal antibody against Gremlin1 can inhibit the activation of FGFR1, thereby suppressing tumor cell proliferation and tumor growth." (PMID 39590377, 2024). "In 50 well-characterized phosphaturic mesenchymal tumours, excessive FGF23 production was attributable to a fibronectin (FN1)–FGFR1 fusion gene in 21 (42%) tumours and in 3 (6%) to a FN1-FGF1 fusion gene." (PMID 38731904, 2024). "Gene fusions involving FGFR1, and various partner genes have been identified in diverse tumor types." (PMID 38831455, 2024). "Infigratinib is a potent and selective inhibitor of FGFR1, 2 and 3 that has demonstrated significant anti-tumor efficacy in preclinical studies." (PMID 38831455, 2024). "Using these data, we analyzed responses to AZD4547 based on the mRNA expression of FGFs (FGF1–23) and FGFRs (FGFR1–4) in EOC patient tumor samples to test for the possible role of these genes as predictive biomarkers for AZD4547." (PMID 38273381, 2024). "Due to structural alterations and dysregulated expression of related factors, FGFR1 signaling can become aberrantly activated in tumor cells through multiple pathways." (PMID 39590377, 2024). "Bevacizumab-resistant tumor cell-derived FGFBP1 induced fibroblast activation protein α expression by enhancing the paracrine FGF2/FGFR1/ERK1/-2/EGR1 signaling pathway in hepatic stellate cells." (PMID 39668826, 2024). "Conventional FGF1 and unconventional FGF2 interact with FGFR3 and FGFR1 on tumours, respectively, which promotes the enhancement of tumour cell invasion mediated by CAFs." (PMID 40135140, 2024). "FGFR1 alterations promote tumor invasion through EMT mechanisms, while CCND1 regulates cell cycle progression through cyclin pathways." (PMID 39410541, 2024). "Constitutive FGFR signaling associated with gains in function in FGF receptors and abnormally high levels of autophosphorylation of FGFR1, play a role in tumor cell proliferation and growth, angiogenesis, and metastasis in various malignancies." (PMID 39590377, 2024). "SCID mice were subcutaneously implanted with four HCC PDX tumours with high FGFR1-4 expression, administered infigratinib (15 mg/kg per day) and sacrificed when tumours were 1800 mm3." (PMID 39144662, 2024).
tumor (continued). "In contrast, the ectopic expression of Fgfr1 in precancerous neuroendocrine cells (preSCs) has been found to increase in vitro cell growth and tumor formation in immune-compromised mice, along with enhanced proliferation-related gene expression changes." (PMID 38892831, 2024). "The implications of FGFR1 manipulation should be assessed in both in vitro tumor organoid models as well as in vivo metastasis models to test the necessity and sufficiency of FGFR1 in the metastatic cascade." (PMID 38827528, 2024). "In cancer cells, N-cadherin inhibits FGF-dependent internalization of FGFR1, retaining it at the membrane and constitutively activating the Erk1/2 pathway, which promotes tumor invasion." (PMID 39796710, 2024). "Fibroblast growth factor receptor 1 (FGFR1) functions as a tumor promoter in various cancers including LC." (PMID 38245787, 2024). "SDC1 exhibited a greater tumor mutational burden (TMB) score, while ERBB2, KDR, FGF2, KIT, FGFR1, and FGF1 showed lower TMB scores." (PMID 38189813, 2024). "Its overexpression via interaction with the fibroblast growth factor receptor 1 (FGFR1) gene slows tumour development, initiates programmed cell death, and controls the cell cycle." (PMID 38915826, 2024). "Among the rest, one tumor each had a ETV6-NTRK3 fusion, a PTEN deletion, an FGFR1 gain-of-function mutation, a CHEK2 LOF mutation (T367fs*), an AURKA-CSTF1 fusion, and a FANCA deletion." (PMID 38730662, 2024). "Of note, in the same analysis, patients with PIK3CAmut tumours that harbour a co‐occurring FGFR1 alteration experienced improved PFS upon treatment with alpelisib + FUL compared to PBO + FUL." (PMID 36892268, 2023). "Fibroblast growth factor receptor 1 (FGFR1) amplification is another key dysregulation in LSCCs and inhibition of FGFR1 in mouse models and cell lines inhibits tumor growth." (PMID 37817767, 2023). "Functionally, genetic knockdown of FGFR1 or pharmacological targeting with erdafitinib, a selective small molecule targeting FGFRs, induced cell cycle arrest, cell death in-vitro, reduced tumor formation, and improved overall survival in-vivo." (PMID 37598282, 2023). "Overexpression of FGFR1 promoted tumor cell growth, migration, invasion, angiogenesis, and metastasis, and was associated with poor prognosis." (PMID 37993879, 2023). "FGFR1 is a member of the FGF receptor family, which is generally associated with tumor invasion, chemotherapy resistance, and poor prognosis." (PMID 37361567, 2023). "Previous studies have demonstrated that dovitinib has potential anti-tumor capability against tumor cell lines with FGFR1 amplification." (PMID 37035154, 2023). "A previous study detected increased expression of FGFR1/2 in bone marrow-derived macrophages (BMDMs) after co-culturing with tumor cells." (PMID 36966334, 2023). "Theoretically, excess of unlabeled peptide saturated the receptor binding sites on the tumor cell surface, meanwhile it bond to the FGFR1 in liver." (PMID 37182162, 2023). "The aim of this study was to investigate the FGF/FGFR1 expression in-between paired tumor-adjacent and tumor tissues from the same patient, and its associations with MBD and tumor characteristics." (PMID 37546410, 2023). "Of the corresponding tumor tissue samples, 287 (70%) displayed positive FGFR1 staining, of which 48 (12%) expressed moderate-high levels." (PMID 37546410, 2023). "FGF2 binds to four receptor tyrosine kinases (FGFR1-4) and acts in a variety of physiological and pathological processes, such as angiogenesis, tumor growth, and development." (PMID 37591843, 2023). "To better understand the relevance of FGFR1 for GBM cell migration and invasion and to identify potential gene-regulatory networks involved in tumor invasion of FGFR1-expressing GBM cells, we performed transcriptional profiling using RNA sequencing (RNA-seq)." (PMID 37579831, 2023).
tumor (continued). "Among these gene/subgroup combinations, there was increased expression of EMP1 and FGFR1 in tumor cells compared to other cells in c9 fibroblasts." (PMID 38187400, 2023). "It is established that the IgLON family member OPCML acts as a tumor suppressor by eliciting the downregulation or the inhibition of RTKs, such as EphA2, FGFR1, FGFR3, HER2, HER4, and AXL." (PMID 37765276, 2023). "We also assayed our model against eight tumours with weak methylation data that clustered alongside controls by consensus clustering, but where we had detected BRAF/FGFR1 variants by targeted sequencing (seven GG and one DNET)." (PMID 36843390, 2023). "This suggests that C26 tumours express some receptors for some exercise-modulated hormones and exerkines such as Fgfr1." (PMID 37840045, 2023). "In the primary tumor S00674, we found a tail-to-tail rearrangement 150 kb upstream of the transcriptional start site of FGFR1." (PMID 37606995, 2023). "The probability of FGFR1-positivity in tumor-adjacent tissues or FGFR1-high levels in tumor tissues was assessed between patients with low and high MBD." (PMID 37546410, 2023). "Of the 426 patients included in the study, 412 (97%) had assessable FGFR1 levels in tumor tissue, 266 (62%) in paired tumor-adjacent tissue, and 327 (77%) had available gene expression data." (PMID 37546410, 2023). "To identify gene regulatory networks related to FGFR1-driven GBM tumor invasion, we compared transcriptomes of control, FGFR1 knockdown, and FGFR2 knockdown GBM cells using RNA-Seq." (PMID 37579831, 2023). "A similar distribution of FGFR1 levels in both tumor-adjacent and tumor tissues was seen across BMI categories at diagnosis." (PMID 37546410, 2023). "Another unique strength is the availability of paired tumor-adjacent and tumor tissues which provided us the opportunity to analyze differences in FGFR1 levels in-between breast epithelial and cancer cells." (PMID 37546410, 2023). "Of note, our analysis identified FGF18 to be expressed in both tumour cell subclusters, interacting with the FGFR1 and FGFR2 receptors of fibroblast subclusters." (PMID 37370765, 2023). "(2019) generated 5 grade 1 PA patient-derived cell lines and found that FGFR1 overexpression alone was able to increase tumor cell migration and drive tumor progression." (PMID 38318325, 2023). "Due to its critical role in tumor growth, FGFR1 has been considered as an important drug target for cancer therapy, and multiple small molecule inhibitors against it have been developed." (PMID 37591843, 2023). "FGFR1 levels were differently expressed in tumor-adjacent and tumor tissues, with increased FGFR1 levels detected in 58% of the tumors." (PMID 37546410, 2023). "Lenvatinib is a first‐line systemic chemotherapeutic agent used in patients with unresectable HCC that inhibits FGFR1–4, thereby reducing tumor stem cells in HCC." (PMID 37750089, 2023). "Our results demonstrate that FGFR1 is up-regulated in MCL, and depletion of FGFR1 alleviates tumor burden and improves survival in-vivo in MCL cell-derived xenograft models." (PMID 37598282, 2023). "Mechanistic studies revealed that zotatifin reprograms the tumor translational landscape, inhibits the translation of Sox4 and Fgfr1, and induces an interferon (IFN) response uniformly across models." (PMID 37874652, 2023). "•Comparative RNA sequencing analysis of control, FGFR1 and FGFR2 knockdown cells revealed gene-regulatory networks relevant for tumor invasion that are specifically associated with FGFR1." (PMID 37579831, 2023). "By inhibiting integrin α5β1, FAK and FGFR1 signaling, the fragments induced tumor cell detachment and reduced cell proliferation." (PMID 37559126, 2023). "The fibroblast growth factor receptors (FGFRs), namely, FGFR1-4, are a family of receptor tyrosine kinases (RTKs) that play important roles in embryonic development, tissue repair, metabolic homeostasis, tumour angiogenesis and proliferation." (PMID 37433897, 2023).
tumor (continued). "Knockdown of FOXQ1 blocked the FGFR1 signaling-stimulated BC cell proliferation, colony formation, and xenograft tumor growth." (PMID 36778115, 2023). "Fgfr1 was most highly expressed and increased uniformly in relation to the tumour proximity, however Fgfr2 - 4 were expressed at low levels and were highly variable." (PMID 37564373, 2023). "The correlation between FGFR1 expression (mRNA) in tumor tissues and FGFR1 expression in corresponding tumor-adjacent and tumor tissues was investigated." (PMID 37546410, 2023). "Herein, we report that paired tumor-adjacent and tumor tissues express FGFR1 differentially, with elevated tumor-specific FGFR1 levels present in nearly 60% of the patients." (PMID 37546410, 2023). "In our study, [18F]F-FGFR1 showed high stability, affinity, specificity and good imaging capacity in cells and tumor-bearing nude mice overexpressing FGFR1, which indicated promise for detecting FGFR1 expression by noninvasive methods." (PMID 37182162, 2023). "MiR‐573 also directly interacts with FGFR1 and reduces its expression levels, thereby inhibiting tumor cell migration, invasion, and EMT." (PMID 37750089, 2023). "FGFR1 is widely expressed, plays important roles in angiogenesis and the phenotype of many types of tumor cells." (PMID 37591843, 2023). "Intriguingly, systematic analysis of mutated tumor genes identified EGFR, MET, BRAF, and TERT as determinants in LUAD, and NOTCH, FGFR1, SOX2, and PI3CA as determinants in LUSC." (PMID 37046851, 2023). "In these tumor cells, we also observed positive staining for p-FGFR1 by IHC, similar to what we had observed in the FGFR inhibitor–sensitive tumor." (PMID 37606995, 2023). "First, we performed immunoblotting on a biological replicate of 2153L tumor samples and observed a dramatic reduction in Sox4 and Fgfr1 protein expression in the zotatifin treatment group." (PMID 37874652, 2023). "In U251 cells, FGFR1 expression promotes tumor growth and invasion via AKT/MAPK and RAC1/CDC42 pathways, respectively." (PMID 37579831, 2023). "Among patients with FGFR1 positive tumor-adjacent tissue, 56% had high MBD (BI-RADS C-D) compared with 63% of patients with FGFR1-negative expression." (PMID 37546410, 2023). "Future studies are warranted to further determine the role of FGFR1 alterations and response to p110α inhibition in PIK3CAmut tumours." (PMID 36892268, 2023). "Overall, NSCLC tumor cells demonstrated higher levels of bFGF and FGFR1-2 protein expression than the histologically normal bronchial epithelium." (PMID 37048074, 2023). "Further, we show that FGFR1 is therapeutically targetable with erdafitinib to achieve lower tumor burdens in multiple in-vivo MCL models to improve overall survival." (PMID 37598282, 2023). "Among the tumor-adjacent tissue samples with assessable FGFR1 levels, 53 (20%) displayed positive staining, of which 2 (1%) expressed moderate-high levels." (PMID 37546410, 2023). "Distribution of patient and tumor characteristics based on FGFR1 expression in tumor-adjacent and tumor tissues." (PMID 37546410, 2023). "The present study was the first to report an intron-derived circRNA from FGFR1 which we found to be overexpressed in PCa to promote tumor cell growth and invasion." (PMID 37993879, 2023). "FGFR1 signaling is involved in multiple pathways that promote cancer cell proliferation, survival, angiogenesis, and tumor progression, making FGFR1 an attractive therapeutic target in cancer treatment." (PMID 37373291, 2023). "In our study, we discovered that elevated FGFR1 expression in GC was positively correlated with tumor immune infiltration and that such overexpressed mouse models were more effectively treated with anti-PD-1 mAb." (PMID 36147913, 2022).